RNU1-47P (RNA, U1 small nuclear 47, pseudogene)
Gene: Small nuclear RNA gene on chromosome 14 (99,945,315 to 99,945,477, forward strand). Ensembl gene ENSG00000199836.
Homologues: Orthologues: chimpanzee U1 (99% identical), macaque U1 (88% identical), rabbit U1 (76% identical), guinea pig U1 (75% identical), mouse Gm22868 (73% identical), pig U1 (67% identical), mouse Gm22826 (65% identical), rat U1 (58% identical). Paralogues in human: RNU1-1 (86% identical), RNU1-2 (86% identical), RNU1-27P (86% identical), RNU1-28P (86% identical), RNU1-3 (86% identical), RNU1-4 (86% identical), RNVU1-18 (86% identical), RNVU1-28 (86% identical), RNVU1-29 (86% identical), U1 (86% identical), RNVU1-31 (85% identical), RNVU1-7 (85% identical), and 134 more.